ETV5 (ETS variant transcription factor 5)
Diseases named in the same sentence as ETV5 in open-access papers (continued):
Sharing a sentence is not in itself a finding about the gene and the disease.
cancer (continued). "Among the top enriched transcription factor motifs, we identified JUN, ETV5, and IRF3, that are well-known to be involved in cancer development." (PMID 35130920, 2022). "The results showed that ETV5 can promote the proliferation, migration, and invasion of HGSOC cells and that it has potential cancer-promoting effects." (PMID 34736492, 2021). "Within this group we observed the ETV4, ETV5 and MYEOV genes which have been shown to promote resistance to MAP Kinase inhibitors as well as promoting cancer cell proliferation, invasion and migration." (PMID 30717152, 2019). "Third, the best known target genes of CIC include PEA3 group genes, ETV1/ER81, ETV4/PEA3, and ETV5/ERM, which are frequently overexpressed in several different types of cancers." (PMID 26124181, 2015). "ETV4 and ETV5, members of the ETS family, are crucial in cancer biology." (PMID 40536817, 2025). "The RNAi against ETV5 significantly suppressed cell proliferation and invasion in the CIC knock-down LNCaP cells, indicating that ETV5 is a critical target of CIC in LNCaP cells in terms of regulation of cancer progression." (PMID 26124181, 2015). "In terms of targeting the proliferation controlled by ELF3 therapeutically, our data would suggest extreme caution as compensatory activation of other ETS family members, most notably ETV5, which is a known oncogene in PCa, could result in cancer progression rather than regression." (PMID 35472129, 2022). "Conversely, ETV5 and SOX9 were not affected by AR-V7 knockdown in CWR-R1 and 22Rv1 cancer cells." (PMID 29069764, 2017).
infection (4 papers, 2015 to 2024). The state of being infected such as from the introduction of a foreign agent such as serum, vaccine, antigenic substance or organism. "Most of the genes downregulated in mouse macrophages during infection appear to be signaling molecules and transcription factors, including ETV5 (ETS transcription factor variant 5), which is downregulated at t6 in all C. gattii isolates except VGIV." (PMID 30355668, 2018). "PU.1 and ETV5 not only participate in the development and differentiation of a variety of immune cells such as T cells, B cells, macrophages, neutrophils, and dendritic cells, but also affect key genes that control infection and inflammation." (PMID 39337492, 2024).
adenocarcinoma (1 paper, 2024). A common cancer characterized by the presence of malignant glandular cells. "While analyzing these CRPC-adenocarcinoma and t-NEPC patients’ individual expression for Pax5, ETV5 and KLF12, we further found that both ETV5 and KLF12 expression vary among adenocarcinoma and t-NEPC patients, with sometimes showing higher expression in CRPC adenocarcinoma." (PMID 39183332, 2024).
neurological diseases (1 paper, 2023). "Furthermore, it was discovered that several targets, such as DLG2, ETV5, PGM3, and ALPK1, were key regulators of neurological diseases." (PMID 36644780, 2023).
ETV5 also shares sentences with these, for which no sentence is quoted: acute myeloid leukemia (1 paper); allergies (1); atherosclerosis (1); Autoimmunity (1); chronic obstructive pulmonary disease (1); cleft lip (1); colon adenocarcinoma (1); endometrial tumour (1); fungal infection (1); lymphoblastic leukemia (1); lymphoma (1); mesothelioma (1); metastatic disease (1); morbid obesity (1); neurofibromatosis (1); prostate tumor (1); renal hypoplasia (1); serous ovarian cancer (1); small cell lung carcinoma (1); thyroid tumor (1); triple-negative breast carcinoma (1); urothelial carcinoma (1).